TNFRSF8 (TNF receptor superfamily member 8)
Diseases named in the same sentence as TNFRSF8 in open-access papers (continued):
Sharing a sentence is not in itself a finding about the gene and the disease.
tumor (513 papers, 2000 to 2026). "RNA sequencing confirmed higher CD30 (TNFRSF8) gene expression levels in high-risk tumours (logFC = 2.3182; FDR = 0.0405)." (PMID 41741970, 2026). "TNFRSF8 (CD30) and CD44 are associated with modulating macrophage activity and promoting tumor migration and invasion, respectively." (PMID 41153362, 2025). "CD30 (TNFRSF8) is a consistent marker of tumor cells but also can be expressed by activated lymphocytes in benign seromas." (PMID 37958303, 2023). "The analysis by IPA of the genes potentially targeted by the identified miRs on the basis of sequence complementarity identified a gene network involving TNFRSF8/CD30 and other genes potentially contributing to defective tumor immunity." (PMID 27983661, 2016). "CD30, also known as TNFRSF8 (tumor necrosis factor receptor superfamily member 8), is a protein receptor that is heavily glycosylated inside the Golgi apparatus, as well as a tumor marker that is found on the surface of specific cells in the body, including certain immune cells and cancer ones." (PMID 37443818, 2023). "CD30 is a transmembrane protein (TNFRSF8) that belongs in the Tumor Necrosis Factor (TNF) family and is abnormally expressed in tumor cells." (PMID 38251321, 2023). "Meanwhile, we show the IHC staining of NRP1, HAVCR2, HHLA2CD44, TNFRSF18, TNFSF14, TNFRSF8, and CD276 in tumor tissues and normal tissues." (PMID 35685438, 2022). "CD30 (TNFRSF8) is a cell membrane protein from the tumor necrosis factor receptor superfamily, which is widely expressed in MF/SS tumor cells." (PMID 33923722, 2021). "All primary HRS cells specifically expressed TNFRSF8 (CD30) and most HRS and bystander cells expressed CD40, highlighting the quality of our data However, only a subset of tumours expressed LTR-driven TNFRSF11A and WNT5A transcripts." (PMID 30546079, 2019). "The results showed that m6Ascore was negatively correlated with the expression of TMIGD2, TNFRSF18, TNFRSF25, TNFRSF4, TNFRSF8, and NRP1, indicating that the poor prognosis of high-m6Ascore patients might be due to the tumor immunosuppressive microenvironment." (PMID 36313417, 2022). "c-Rel-dependent regulation of expression of eTreg-associated molecules, such as Integrin α E (Itgae), Tigit, Klrg1, Il1r2, and TNF receptor superfamily member 8 (Tnfrsf8), may contribute to eTreg-mediated anti-tumor functions, rather than immune homeostasis." (PMID 31434282, 2019). "Moreover, the upregulation of TNFRSF1B, TNFRSF8, TNFRSF9, and TNFRSF10 expression, as well as elevated levels of TNF, suggested apoptotic signal transition through the TNF family membrane receptors, which was also detected in tumour cells treated with chemotherapeutic drugs." (PMID 35804353, 2022).
cancer (111 papers, 2006 to 2025). A tumor composed of atypical neoplastic, often pleomorphic cells that invade other tissues. "We demonstrate here that cancer-specific TNFRSF8 glycosylation is associated with malignant lung nodules." (PMID 37444527, 2023). "Moreover, cancer testis antigens and TNFRSF8 (CD30) were among the downregulated genes potentially reflecting reduced HRSC content." (PMID 38836098, 2024). "In various types of cancer, findings between NNMT and immunostimulator gene expression showed a high connection (p < 0.05), including TNFSF13B, TNFRSF8, TNFSF14, IL6, IL2RA, CD80, CD27, and CD86." (PMID 36386816, 2022). "Correlation analysis between RFC4 and checkpoint gene expression in different types of cancers showed a high correlation with immune genes including CCL4, CCL16, HLA family genes, TNFRSF8, TNFRSF14, TNFRSF18, CD70, CD44 (p < 0.05), CD276, CX3CL1 and VGEGFA (p < 0.05)." (PMID 39031628, 2024). "In diverse cancer types, the correlation between OAS3 and the expression of checkpoint genes indicated a high correlation with TNF-related immune genes including TNFRSF14, TNFRSF8, TNFRSF25, TNFRSF4, TNFRSF18, TNFSF15, and TNFRSF9." (PMID 35592250, 2022). "In diverse cancer types, correlation analysis between CDCA4 and checkpoint gene expression indicated a high connection (P<0.05) with TNF-related immune genes including TNFRSF8, TNFRSF14, TNFRSF18, CD70, CD44, and CD276 (B7-H3)." (PMID 35251007, 2022). "TNFRSF8 shows significant upregulation in MDA-MB-231, T-47D, and U-937 cancer cell lines, but not in MCF-7 or HSF cells, indicating its strong immune-related response specifically in cancer cells." (PMID 39805861, 2025).
infection (23 papers, 2012 to 2025). The state of being infected such as from the introduction of a foreign agent such as serum, vaccine, antigenic substance or organism. "The results exhibited that differential expression of both LNC_000428 and Tnfrsf8 were induced by S2308 infection in RAW264.7 cells, and that differential lncRNA expression at 48 hpi was definitely higher than the outcomes at 4, 8 and 12 hpi." (PMID 36494502, 2022). "Many up-regulated genes are closely related to inflammation and immune responses, such as CCL20, IL6, CXCL1, CSF1R, CCR5, TNFRSF8, indicating that mice infected N. farcinica via these two infection routes may lead to robust inflammatory response." (PMID 40723822, 2025). "Besides that, relative RNA expression of LNC_000428 and Tnfrsf8 were significantly reduced in the two cell lines with an infection of S2308 for 48 h." (PMID 36494502, 2022). "Therefore, spatio‐temporal expression of LNC_000428 and its anti-sense gene Tnfrsf8 in RAW264.7 cells with S2308 infection, were determined by qRT-PCR." (PMID 36494502, 2022). "Furthermore, Tnfrsf8, as a well-known CD30, was predicted as one of the targets of anti-sense lncRNA LNC_000428, which was upregulated in B. abortus-infected RAW264.7 cells at 24 hpi and mouse spleens at 24 h post-infection." (PMID 36494502, 2022).
TNFRSF8 also shares sentences with these, for which no sentence is quoted: anaplastic large cell lymphoma (350 papers); mycosis fungoides (84); lymphoproliferative disorders (82); peripheral T-cell lymphoma (60); cutaneous T-cell lymphoma (53); diffuse large B-cell lymphoma (46); Lymphomatoid Papulosis (43); classical Hodgkin lymphoma (37); hematological malignancies (29); germ cell tumor (20); melanoma (18); Sézary syndrome (18); seminoma (16); viral infection (15); adult T-cell leukemia/lymphoma (12); angioimmunoblastic T-cell lymphoma (12); multiple myeloma (11); lymphoid neoplasm (8); T-cell leukemia (8); yolk sac tumor (8); atopic dermatitis (7); Burkitt lymphoma (7); EATL type I (7); hematological cancers (7); mastocytosis (7); NK-T cell lymphoma (7); T-cell neoplasm (7); chronic lymphocytic leukemia (6); celiac disease (5); follicular lymphoma (5).
A further 244 diseases each share a sentence with TNFRSF8 in 5 papers or fewer.